FALEC (focally amplified lncRNA regulator of ECM1)
Synonyms: ncRNA-a1; FAL1; LINC00568
Gene: Long non-coding RNA gene on chromosome 1 (150,515,667 to 150,537,267, forward strand). Ensembl gene ENSG00000228126.
Diseases named in the same sentence as FALEC in open-access papers:
FALEC is named in the same sentence as 10 diseases in open-access papers, as found by Europe PMC text mining. Sharing a sentence is not in itself a finding about the gene and the disease. The quoted sentences say what the papers report.
endometrial carcinoma (1 paper, 2022). A malignant tumor arising from the epithelium that lines the cavity of the uterine body. "In previous studies, Zheng’s research confirmed that FALEC is significantly expressed in endometrial carcinoma tissues and cells and plays a role in cell proliferation and cell cycle regulation." (PMID 35237659, 2022).
gastric tumors (1 paper, 2018). "Consistent with our results, we also found overexpression of lncRNAs such as H19, GAS5, TUG1, AP5M1 and MALAT1 and downregulation of LINCROR, POU3F3, HOTAIR, FALEC, NBAT1, and ZEB2-AS1 lncRNAs in TCGA gastric tumor datasets." (PMID 29719612, 2018).
melanoma (1 paper, 2023). A malignant, usually aggressive tumor composed of atypical, neoplastic melanocytes. "Moreover, FALEC expression may be used as an independent prognostic marker for melanoma patients, since its expression has been linked to metastasis, TNM (tumor, node, metastasis) stages and overall patients survival." (PMID 37325482, 2023).
preeclampsia (1 paper, 2022). Preeclampsia is a hypertensive disorder of pregnancy that is characterized by new-onset hypertension with proteinuria presenting after 20 weeks of gestation, and depending on mild or severe forms may initially present with severe headache, visual disturbances, and hyperreflexia. "As noncoding RNAs are an important part of evolutionary genetics and have been confirmed to play regulatory roles in preeclampsia, seven lncRNAs reported to be associated with hypoxia were selected, including UCA1, EFNA3, H19, MALAT1, HOTAIR, FALEC, and HAS2-AS1." (PMID 36160709, 2022).
tumor (5 papers, 2018 to 2023). "The results showed that FALEC expression was lower in tumor tissues than in normal tissues and associated with positive prognosis in the TCGA datasets." (PMID 31335317, 2019). "In the present study, we observed significant downregulation of FALEC in TSCC tissues compared to tumor adjacent normal samples." (PMID 31335317, 2019). "In the present study, we found that the expression of FALEC was significantly upregulated in GC tissues compared with paired adjacent non-tumor tissues." (PMID 30984243, 2019). "However, little is known about the detailed function and mechanism of FALEC in cis in tumorigenesis and tumor development." (PMID 30984243, 2019). "The data revealed that FALEC acted as a tumor suppressor in TSCC and may aid in developing a novel potential therapeutic strategy against TSCC." (PMID 31335317, 2019). "The results showed that compared with the adjacent non-tumor control, FALEC RNA level was significantly higher in the CCA tissue samples, and further the expression of FALEC was higher in the 5-fluorouracil (5-FU) resistant patients." (PMID 37166421, 2023). "Furthermore, other lncRNAs such as FALEC was also reported as a tumor-suppressor with low expression in OSCC, and the overexpression of FALEC significantly repressed OSCC cell proliferation and migration both in vitro and in vivo, and this predicts a good prognosis in OSCC patients." (PMID 34885054, 2021).
FALEC also shares sentences with these, for which no sentence is quoted: gastric cancer (2 papers); cancer (1); digestive system tumors (1); lymph node metastasis (1); thyroid (1).